INS (insulin)
Diseases named in the same sentence as INS in open-access papers (continued):
Sharing a sentence is not in itself a finding about the gene and the disease.
Hyperglycemia (continued). "Alloxan acts as diabetogenic by the destruction of the beta-cells of islets of Langerhans and causes a massive reduction in insulin release, thereby inducing hyperglycemia." (PMID 36624877, 2022). "This previous study showed that BEZ treatment markedly attenuated hyperglycemia, decreased plasma lipids as well as improved glucose and insulin tolerance; however, the underlying molecular mechanisms were not completely understood." (PMID 35327418, 2022). "If the foetus does not inherit the mutation, the foetal pancreas will sense the maternal hyperglycaemia and increase insulin secretion, leading to increased foetal growth and birth weight." (PMID 35445424, 2022). "SDT rats are an inbred strain of Sprague–Dawley rat that spontaneously develop hyperglycemia, glucose intolerance, and deficient insulin production owing to β-cell degeneration." (PMID 36008962, 2022). "Exercise allows muscles to uptake glucose in an insulin-independent manner, highlighting their capacity to ameliorate hyperglycemia even in the condition of insulin deficiency or resistance." (PMID 35929791, 2022). "Postprandial hyperglycemia arises from delayed and deficient insulin secretion as well as impaired suppression (or a paradoxical rise) of glucagon concentrations." (PMID 35822422, 2022). "This disease is associated with a violation of the absorption of glucose and develops due to a deficiency of the hormone insulin, resulting in the development of hyperglycemia, a persistent increase in blood glucose." (PMID 36557956, 2022). "This is in contrast to the less selective pasireotide which has potent activity for SST5 receptor and is causally associated with decrease in insulin secretion and hyperglycemia." (PMID 35000098, 2022). "The etiology of T2DM and the associated hyperglycemia can be broadly attributed to the progressive impairment of insulin sensitivity, in concert with the dysfunction of pancreatic β-cells." (PMID 35208623, 2022). "T1DM is caused by an autoimmune-mediated destruction of the insulin-producing pancreatic beta cells leading to hyperglycemia through insulinopenia." (PMID 35244142, 2022). "It is characterized by hyperglycemia which is associated with altered insulin secretion, leading to morbidity, dysfunction and failure of the normal functioning of vital organs, especially the eyes, liver, kidney, nerves, heart, etc.." (PMID 35164215, 2022). "We found the disorganization in the areas of cellular damage and synaptic loss indicates the psychological deficit which strongly associated with hyperglycemia and altered signaling of insulin." (PMID 36302045, 2022). "The development of stress hyperglycemia is caused by transient insulin resistance and a highly complex interplay of counter-regulatory hormones such as catecholamines, growth hormone, cortisol, and cytokines." (PMID 35209920, 2022). "Type 1 diabetes (T1D) is an autoimmune disease characterized by the destruction of insulin-producing β-cells in the pancreas, leading to progressive insulin deficiency and consequent hyperglycemia." (PMID 36451229, 2022). "The underlying mechanisms are manifold: besides hyperglycemia and elevated blood insulin levels with the stimulation of the IGF-1 pathway, several adipokines, secreted by the adipose tissue, promote carcinogenesis." (PMID 36547172, 2022). "Hyperglycemia during admissions in patients with T2DM is often treated with insulin, which is considered a ‘high-risk’ medication due to the risk of hypoglycaemia." (PMID 35162066, 2022). "This insulin-deficient rat model exhibits characteristics of moderated hyperglycemia and is associated with a loss of 60% of the function of β-cells." (PMID 36296494, 2022). "T2DM, whose main feature is hyperglycemia, is caused by a combination of defects in the secretion and peripheral action of insulin." (PMID 36355175, 2022). "T2D is characterized by hyperglycemia caused by resistance to insulin action and an inadequate compensatory insulin secretory response." (PMID 36348470, 2022).
Hyperglycemia (continued). "Induction of T2DM caused a significant weight loss and destruction of pancreatic islets, which affected insulin-producing β-cells and resulted in hyperglycemia compared to healthy control group (p < 0.001)." (PMID 35401218, 2022). "STZ destroys β-cells in pancreatic islets, which causes insufficient INS production and secretion leading to hyperglycemia." (PMID 36119371, 2022). "As far as the optimal treatment of gestational hyperglycemia is concerned, insulin is necessary if only the mother carries an HNF1A mutation." (PMID 35052457, 2022). "Stage 2 is damage to the pancreatic β-cells causing pre-symptomatic hyperglycemia, and stage 3 is overt T1D due to pancreatic β-cell failure with a requirement for exogenous insulin." (PMID 36421377, 2022). "Although significant progress has been made in this regard, insulin replacement therapy is only so effective at preventing prolonged periods of hyperglycemia and continues to suffer from the risks associated with hypoglycemia." (PMID 35336018, 2022). "Through the binding in the pancreatic cells, apha-2- agonists decrease insulin secretion that causes hyperglycaemia in adult horses." (PMID 35818051, 2022). "In T2D, these cells become inoperative in order to compensate for insulin resistance, resulting in an insulin-deficient condition called hyperglycemia." (PMID 35807558, 2022). "Consistent with epidemiological studies, in vivo OPP exposure caused hyperglycemia in rodents, but data on plasma insulin levels were variable." (PMID 35156417, 2022). "Many researchers have focused on the ability of CPF to cause hyperglycemia where exposure to CPF decreased serum insulin levels and increased serum glucose levels (hyperglycemia)." (PMID 35457505, 2022). "Hyperglycemia can result in glucose toxicity that further deteriorates the function of beta cells of the pancreas, giving rise to a deficiency of insulin in the body." (PMID 35807558, 2022). "Athletes with T1DM are encouraged to reduce their insulin doses before exercise to prevent hypoglycaemia, however care also needs to be taken to prevent a deficiency of insulin which would lead to hyperglycaemia and ketosis." (PMID 36425473, 2022). "Diabetic mice, in the current study, had demonstrated significant hyperglycemia associated with a decrease in insulin level." (PMID 36316746, 2022). "In the present study, high fat diet, streptozotocin-induced T2DM caused obliteration in the insulin action, thus affecting the plasma glucose regulation and resulting in hyperglycemia." (PMID 36290804, 2022). "Hyperglycemia causes an increased glucose uptake in cells relying on insulin-independent GLUT transport, e.g., endothelial cells." (PMID 35883827, 2022). "The liver is the major site for glucose and lipid metabolism, and hepatic insulin resistance is thought to be one of the main causes of fasting hyperglycemia." (PMID 35721172, 2022). "In the treatment of hyperglycemia caused by steroids, insulin can be used alongside oral hypoglycemic drugs." (PMID 35582516, 2022). "Its deletion in adult murine islet cells causes hyperglycemia, with reduced expression of insulin, a process that was attributed to the loss of beta-cell function and the expansion of alpha-cells." (PMID 35681432, 2022). "Early disturbances in insulin sensitivity and hyperglycemia (HG) are risk factors for the development of diabetes, which is a global burden with increasing prevalence." (PMID 36386326, 2022). "The symptomatic stage of T1D manifests as polyuria, polydipsia due to hyperglycemia, and eventually ketoacidosis caused by excessive lipolysis due to insulin deficiency and can only be treated with insulin replacement therapy." (PMID 35844538, 2022). "Several studies reported that any defect in glucose-sensing machinery would impair insulin secretion, which causes severe hyperglycemia." (PMID 36101450, 2022).
Hyperglycemia (continued). "For instance, hyperglycemia and impaired insulin regulation increase ANG II, causing to myocardial hypertrophy, fibrosis, and apoptosis." (PMID 35204118, 2022). "DM is a group of metabolic diseases marked by hyperglycemia, which is caused by changes in insulin production, insulin action, or a combination of both." (PMID 35233335, 2022). "β-cell metabolic stress is a comprehensive concept mediated by hyperglycemia, hyperlipidemia, and hyperinsulinemia and is caused by excessive energy intake and insulin resistance in peripheral tissues." (PMID 35929791, 2022). "DM refers to a group of chronic metabolic diseases characterized by hyperglycemia and dysfunction or destruction of pancreatic β-cells, causing defects in insulin secretion, insulin action, or both." (PMID 35406040, 2022). "Diabetic-associated obesity is a metabolic disorder caused by changes in insulin secretion and characterized by persistent hyperglycemia and disturbances in carbohydrate, protein, and lipid metabolism." (PMID 35462799, 2022). "Mediation effect of insulin on the association between BMI and intermediate hyperglycemia adhering to the principles of Baron and Kenny and by using the standard equation modeling analysis, adjusted for age and sex." (PMID 35757631, 2022). "In type 1 diabetes (T1D), hyperglycemia results from a loss of insulin production caused by pancreatic β-cell dysfunction and/or destruction as a result of an autoimmune process." (PMID 35303528, 2022). "It is a heterogeneous class of diseases associated with metabolism resulting from faulty insulin secretion and/or action, leading to eventually pave the way toward hyperglycemia." (PMID 36293291, 2022). "This occurs when either the body is unable to make insulin, causing hyperglycemia, or when the body cannot use insulin efficiently." (PMID 35890541, 2022). "Vit D has been linked to the development of T2DM, presumably by altering insulin secretion and, as a result, hyperglycemia." (PMID 35733163, 2022). "In the case of pregnant women presenting heterozygous loss-of-function mutations and an unaffected child, the increased insulin secretion and insulin-stimulated growth secondary to maternal hyperglycemia can increase the risk of fetal macrosomia." (PMID 36361703, 2022). "Polymorphisms in this gene have been related to T2DM risk because of hyperglycaemia derived from impaired insulin secretion." (PMID 36314849, 2022). "Higher levels of salivary CRP and insulin (OR 4.97 [95%CI: 1.66,14.90]; p = 0.004, OR 2.64 [95%CI: 1.09,6.38]; p = 0.03, respectively) were associated with intermediate hyperglycemia." (PMID 35757631, 2022). "Hyperglycemia is potentially detrimental in critically ill humans, and numerous studies have investigated the use of insulin to control sepsis-associated hyperglycemia in humans." (PMID 35802586, 2022). "This disease is a public health problem characterized by high blood sugar concentrations (hyperglycemia) associated with impaired insulin sensitivity in the liver, skeletal muscle, and adipose tissue and reduced insulin secretion." (PMID 35648976, 2022). "It is characterized by hyperglycemia because of the deficient action of insulin on the target organ or its secretion from pancreatic β-cell leading to metabolic disorder in proteins, carbohydrates, and fats; irreversible injury; and organ dysfunction." (PMID 35345832, 2022). "T2DM is primarily a disease of hyperglycemia due to a deficiency of insulin’s many functions, but serum lipids are also strongly affected by insulin." (PMID 36142760, 2022). "Type 1 diabetes (T1D) is characterized by the immune-mediated destruction of insulin-producing beta cells in the pancreatic islets, leading to insulin deficiency and hyperglycemia." (PMID 35407396, 2022). "The reduction of insulin sensitivity is associated with a decrease in mass and function of insulin-producing pancreatic β–cells, leading to gradual high blood glucose or hyperglycemia." (PMID 33880430, 2021).
Hyperglycemia (continued). "Hyperglycaemia is a key factor underlying DN, but other changes also contribute, including dyslipidaemia and changes in insulin signalling." (PMID 33436718, 2021). "Calcineurin-knockout mice exhibited severe hyperglycaemia with increasing age as well as dysregulation of specific genes like insulin and others implicated in the maintenance of β-cell mass." (PMID 34638652, 2021). "Hyperinsulinemia and the decrease of hepatic insulin clearance secondary to NAFLD are associated with increased hepatic gluconeogenesis, hyperglycemia, and insulin overproduction, a pathological self-reinforcing cycle." (PMID 33505944, 2021). "The lower doses are associated with lower risk of adverse effects with almost unaffected benefits in terms of improving hyperglycemia and insulin sensitivity, and lowering cancer risk in both direct and indirect mechanisms." (PMID 33562380, 2021). "Insulin regulates the blood glucose level (BGL); low secretion of insulin causes hyperglycemia, which enhances oxidative stresses and eventually causes several health problems like frequent urination, thirst, and hunger." (PMID 33669341, 2021). "Before the first dose of study drug, he received subcutaneous insulin due to sepsis-associated hyperglycemia." (PMID 34020705, 2021). "Intensive insulin therapy in T1D replaces the beta cell deficiency and corrects fasting and postprandial hyperglycemia, but at increased risks of hypoglycemia." (PMID 34659118, 2021). "IR also causes stress to the insulin producing beta cells which, as a consequence of the IR state, are required to produce more insulin to compensate for hyperglycemia." (PMID 34902055, 2021). "The use of opioids in animal models can bring other harmful adverse effects to them, such as hormonal changes and increase or decrease food intake, and can act through the sympathetic nervous system to cause hyperglycemia and decreased secretion of insulin." (PMID 33915847, 2021). "The advantage of using PACIRKO mice is that it removes the confounding effects of hyperglycaemia or loss of systemic insulin secretion which occurs in Ins2Akita mice." (PMID 34282152, 2021). "Loss of beta-cells leads to insulin insufficiency and hyperglycemia, with patients eventually requiring lifelong insulin therapy to maintain normal glycemic control." (PMID 34691077, 2021). "In general, hyperglycemia leads to body weight increase, adiposity, and general malaise caused by increased blood insulin levels." (PMID 32772168, 2021). "We next wanted to separate the confounding effects of hyperglycaemia, or reduced systemic insulin, from a loss of any direct protection of insulin on acinar cells." (PMID 34282152, 2021). "It is recognized as a group of varied disorders with the common elements of glucose intolerance, hyperglycemia caused by insulin shortage, reduced efficacy of insulin action, or both." (PMID 33510964, 2021). "Insufficiency of the insulin activation level principally causes hyperglycemia, commonly determined in T2D patients." (PMID 34502417, 2021). "Patients with HNF1A heterozygous mutations show β cell dysfunction and hyperglycemia due to insufficient insulin release in response to increased blood glucose levels." (PMID 34295307, 2021). "This can be attributable to the morning hyperglycemia, i.e., the dawns phenomenon along with rising demand for insulin linked with a nocturnal growth hormone surge." (PMID 34737903, 2021). "It is caused by impaired insulin secretion and/or action and is characterised by chronic hyperglycaemia affecting the metabolism of carbohydrates, fats and proteins." (PMID 34684518, 2021). "Post-stroke hyperglycemia is associated with increased insulin resistance and β-cell death after ischemic stroke, and it exacerbates brain damage by increasing oxidative stress and inflammation in ischemia-induced gerbils." (PMID 33494481, 2021). "NRF2-deficient mice are characterised by lower basal insulin levels and longer periods of hyperglycemia." (PMID 33893069, 2021).
Hyperglycemia (continued). "Nrf2, as a master regulator of antioxidant response elements by activating cytoprotective genes expression, is decreased oxidative stress that associated with hyperglycemia and increases insulin sensitivity." (PMID 33468193, 2021). "More recently a large study from the National Swedish EXPRESS Cohort demonstrated, insulin treatment of hyperglycaemia in the first 28 days of life, was associated with lower 28- and 70-day mortality." (PMID 34368024, 2021). "On the contrary, the standard insulin treatment, although obtaining the correction of hyperglycemia in a longer time interval, is likely less capable of causing hypoglycemic peaks." (PMID 34659090, 2021). "Studies have shown increased NOX activity to be associated with impaired calcium signaling and hyperglycemia-induced cardiomyocyte apoptosis and mitochondrial dysfunction, as well as the regulation of insulin secretion in pancreatic cells." (PMID 34575050, 2021). "Thirty mg/kg of STZ producedsignificant hyperglycemia, but didnot cause significant insulin resistance in the animal model studied." (PMID 34431921, 2021). "This chronic health condition is characterized by hyperglycemia which results from defects in glucose homeostasis stemming from relative or absolute deficiencies in insulin." (PMID 34458216, 2021). "Type 1 diabetes (T1D) is characterised by immune-mediated destruction of insulin-producing pancreatic beta cells leading to loss of insulin production and hyperglycaemia." (PMID 34521982, 2021). "MODY3 patients develop β-cell dysfunction and hyperglycemia caused by impairment of glucose-dependent insulin secretion." (PMID 34079523, 2021). "A pre-reviewed paper in BioRxiv showed maternal exposure to PM2.5 increased DNA methylation in pancreatic islets associated with the reduced blood insulin level and hyperglycaemia, which is an effect lasting for two generations." (PMID 34066412, 2021). "GIP receptor agonism and GLP-1 receptor agonism limit the hyperglycemia caused by glucagon and improves insulin sensitivity." (PMID 34577569, 2021). "One group of abnormalities, all seen in untreated type 1 diabetes, such as hyperglycaemia and occasionally ketoacidosis, can be attributed to loss of insulin action." (PMID 34841432, 2021). "Poor nocturnal glycemic control can cause a reduced sensitivity of insulin at liver and other tissues, leading to fasting hyperglycemia, which is the cornerstone of all-round glycemic control throughout the day." (PMID 34702362, 2021). "Second, hypoxia demonstrated significant increases in plasma glucose and insulin; however, intermittent or prolonged hypoxia can increase insulin resistance in genetically obese mice that causes reflex hyperglycemia." (PMID 35052543, 2021). "Treatment of hyperglycemia with chemical drugs or insulin causes several side effects such as chronic anorexia, cerebral atrophy and insulin-induced fatty liver." (PMID 34120609, 2021). "In type I diabetic mice, the hybrid patch can effectively control hyperglycemia and mini mize the risk of hypoglycemia in the settings of insulin therapy with insulin overdose or simulated delayed meal." (PMID 36338772, 2021). "β-cell death has also been reported to underlie loss of insulin secretory capacity and hyperglycemia in mouse models of T2D." (PMID 34822454, 2021). "The objective of this study was to assess incretin-based therapy versus insulin for managing pasireotide-associated hyperglycemia uncontrolled by metformin/other permitted oral antidiabetic drugs." (PMID 34275099, 2021). "It describes a group of chronic metabolic disorders characterized by persistent high blood sugar levels (hyperglycemia) caused by insulin resistance, inadequate secretion of insulin or excessive secretion of glucagon." (PMID 33767633, 2021).